SKP2 (S-phase kinase associated protein 2)
Diseases named in the same sentence as SKP2 in open-access papers (continued):
Sharing a sentence is not in itself a finding about the gene and the disease.
tumor (continued). "They jointly result in the uncontrolled upregulation of SKP2, which may favour cell transformation and tumour progression." (PMID 27779207, 2016). "Importantly, multiple studies using Skp2 knockout mice have demonstrated that Skp2 is required for spontaneous tumor development that occurs in the pRb, Pten and p19Arf deficient mouse models." (PMID 26497688, 2015). "6-OAP also induced downregulation of NIPA and Skp2 and up-regulation of Cyclin B1 in tumor samples." (PMID 26474281, 2015). "Furthermore, the overexpression of CDX2 upregulated the expression of Bax and downregulated the expression levels of survivin, Bcl-2, cyclin D1, Skp2 and c-Myc in the tumor tissues." (PMID 25738600, 2015). "Indeed, deficiency of Akt E3 ligases including Skp2, TRAF6 and TRAF4 suppresses tumor growth in vivo." (PMID 25309720, 2014). "It has been reported that aberrant STAT3 activation promotes uncontrolled tumor cell growth and survival through multiple mechanisms, including increased expression of oncogenes, such as c-myc, Skp2, and cyclin D1, as well as antiapoptotic proteins, including Bcl-2, Bcl-xL, Mcl-1, and survivin." (PMID 24386318, 2013). "A correlation between Ki67 and SKP2 has been found in several tumor types, including GIST." (PMID 23690967, 2013). "Future study is directed to mechanistically understand how and whether SIRT3 exerts its tumor suppressor function by inactivating the Skp2 oncogenic pathway solely in a deacetylase-dependent manner." (PMID 23230084, 2012). "Our data suggests that Skp2 expression might be a new prognostic biomarker for tumor recurrence in ESCC patients." (PMID 22533738, 2012). "Surprisingly, loss of Skp2 in the same mouse model also resulted in elevated p27Kip1 levels but exhibited no impact on tumor onset." (PMID 22624029, 2012). "Knockdown of SKP2 significantly reduced tumor formation and metastasis of breast cancer xenografts." (PMID 23226679, 2012). "Moreover, we found that the SIRT3 tumor suppressor serves as the physiological deacetylase that antagonizes p300-mediated Skp2 acetylation." (PMID 23230084, 2012). "Multivariate analysis showed that cytoplasmic Skp2 expression (HR = 1.662, 95% CI 1.027–2.690, p = 0.039) parallels prognostic indicators of metastasis, as do tumor size (HR = 1.164, 95% CI 1.063–1.274, p = 0.001) and lymph node status (HR = 3.835, 95% CI 2.158–6.813, p = 0.000)." (PMID 23300741, 2012). "A recent study in mice revealed that inactivation of SKP2 induces tumour cell senescence that is dependent upon p27, p21 and the transcription factor ATF4, which is an integral component of the unfolded protein response (UPR) that is activated in response to endoplasmic reticulum stress." (PMID 21182779, 2010). "Skp2 over-expression is the main factor involved in deregulation of p27Kip1, and Skp2 is also a regulator of other cell cycle proteins that are involved in tumor progression; therefore, it may also have important influence on drug resistance." (PMID 18644126, 2008). "Interestingly Skp2 expression correlated with cellularity (p = 0.05), tumour size (p = 0.01), mitotic count (p = 0.05) and Ki67 (p = 0.01)." (PMID 18474118, 2008). "Tumor studies in skp2 knockout mice and specifically in skp2 heterozygous mice could shed light on these questions." (PMID 17488529, 2007). "Skp2 is elevated in a range of tumours, where our data indicate it may play a separable but complementary role in regulating cell cycle progression and differentiation." (PMID 18081928, 2007). "Furthermore, another key tumor suppressor downregulated by skp2 is the negative cell cycle regulator p27 encoded by CDKN1B which was also shown in our study to be upregulated by the combination." (PMID 38489280, 2024). "A natural Skp2 inhibitor with high affinity and specificity, which could disrupt the binding between Skp2 and other proteins, might be a potential effective Skp2 inhibitor in tumor treatment, or used as template for developing more potent and safer drugs." (PMID 37089937, 2023).
tumor (continued). "Therefore, Skp2 could promote tumor cell proliferation and invasion in tumor cells, mainly acting as an oncogene." (PMID 35845132, 2022). "Thus, Skp2 has been proposed as an attractive target for anti-tumor interventions." (PMID 35301297, 2022). "In addition, it has also been reported that a variety of natural compounds, such as curcumin, quercetin, lycopene, epigallocatechin-3-gallate, vitamin D3, dioscin, gartanin, and flavokawain A inhibit the expression of Skp2 and subsequently exert anti-tumor activity." (PMID 34068643, 2021). "Additionally, E2F1 and SKP2 are highly expressed in multiple tumour cells collaboratively." (PMID 34428336, 2021). "Also expression of SKP2 in different tumor stages was statistically insignificant." (PMID 32856866, 2020). "Previous research indicated that Wnt7a could inhibit tumor by regulating SKP2/P21 signaling." (PMID 31886205, 2019). "Additionally, E2F and SKP2 highly express in multiple tumor cells in a collaborative manner." (PMID 31357480, 2019). "Furthermore, researchers have also found that the p27 and SKP2 pathway may act as the inhibitors of tumor progression in RB function." (PMID 28337249, 2017). "SKP2 is the S-phase kinase associated protein 2 involved in cell cycle progression; it is the component of the SCF complex that confers substrate specificity to E3 ligase for ubiquitination of many targets that are tumour suppressors, which are marked for degradation in the proteasome." (PMID 26682011, 2016). "Subsequently, we investigated whether SKP2 synergizes with AKT for tumor development in mice." (PMID 25537506, 2015). "In addition to destabilizing c-MYC as reported herein, SIRT3 could function as a tumor suppressor possibly via its ability to deacetylate the proto-oncogene Skp2." (PMID 26317998, 2015). "Data showing a role for the ubiquitin ligases β-TrCP, FBW7, Huwe1, and SKP2 in MBs suggest the possibility of a classification of MBs based on the expression (over expression or under expression) of specific ubiquitin ligases which function as oncogenes, tumor suppressors or cell cycle regulators." (PMID 26475605, 2015). "Therefore, our findings suggest that a downregulation of BIS expression could serve as a potential strategy for restricting tumor progression via an induction of senescence through the regulation of STAT3/SKP2/p27 pathway." (PMID 25412315, 2014). "Uncontrolled SKP2 upregulation may favor cell transformation in vitro and tumor progression." (PMID 25310357, 2014). "Furthermore, cytoplasmic Skp2 expression (HR = 2.084, 95% CI 1.217–3.568, p = 0.007) also parallels prognostic indicators of survival, as well as tumor size (HR = 1.166, 95% CI 1.061–1.283, p = 0.002) and lymph node status (HR = 3.542, 95% CI 1.901–6.598, p = 0.000)." (PMID 23300741, 2012). "In this large scale study, we evaluated whether there is an association between tumor cell expression of Jab1, p16, p21, p62, Ki67 and Skp2 and survival in 193 non-GIST STS patients." (PMID 23071715, 2012). "Thus, high expression of Skp2 was associated with loss of tumor differentiation and negative ER or PR expression." (PMID 18644126, 2008).
tumor (continued). "Among many genes in this pathway, SKP2 was found over-expressed in basal-like tumors; it encodes a protein involved in the degradation of another cyclin-dependent kinase inhibitor p27 (CDKN1B) and recently reported to be over-expressed in many tumor types and to correlate with poor prognosis." (PMID 16729877, 2006). "Taken together, these results suggest that SKP2 overexpress induces the remodeling of ECM and creates an immune suppressive prostatic microenvironment to support tumor initiation and development." (PMID 41542047, 2026). "Overall, these findings delineate a tumor-intrinsic signaling axis in which PD-L1 upregulates Livin and Galectin-1 to sustain PI3K/AKT activity and drive SKP2-dependent cell proliferation." (PMID 41898602, 2026). "This relationship is also evident in GBM, where studies have shown that overexpression of Skp2 promotes the EMT phenotype, suggesting its significant role in tumor progression and treatment resistance." (PMID 39744562, 2025). "TRβ1 has been proposed to function as a tumor suppressor by downregulating EMI1 and SKP2 to inhibit cell cycle progression and prevent aberrant proliferation." (PMID 40605078, 2025). "Through interaction with C‐MYC in the nucleoplasm, PDCD11 hinders C‐MYC‐induced SKP2 from binding to the C‐MYC MB2 domain for ubiquitination, thereby stabilizing C‐MYC to drive tumor progression." (PMID 40051297, 2025). "By antagonizing SKP2‐mediated C‐MYC ubiquitination, PDCD11 disrupts the balance between C‐MYC and SKP2, resulting in uncontrolled C‐MYC signaling and tumor progression." (PMID 40051297, 2025). "PDCD11 silencing restores SKP2‐mediated C‐MYC degradation, thereby remarkably suppressing tumor growth and metastasis in nude mice." (PMID 40051297, 2025). "Conversely, oncogenic F-box proteins such as SKP2 and FBXO22 promote cancer cell proliferation and metastasis by degrading tumor suppressors or stabilizing hypoxia-inducible factors, respectively." (PMID 40534867, 2025). "Transcriptional analysis showed a marked downregulation of key genes involved in tumor cell growth and proliferation, including CDK1, CDK2, and CDK6 (up to a 31.11‐fold decrease), PLK1 (up to a 21.49‐fold decrease), and SKP2 (up to a 14.68‐fold decrease)." (PMID 41221154, 2025). "By accelerating CCND1 degradation through SKP2-mediated ubiquitination, MAT1A depletion disrupts the delicate balance between cell proliferation and apoptosis, thereby impairing tumor growth." (PMID 39438468, 2024). "Our analysis revealed that the upregulation of the SKP2 E3 ligase leads to excessive degradation of BRCA2, potentially promoting tumor cell proliferation and metastasis." (PMID 39062881, 2024). "Apart from SKP2, ITGB4, CDKN3, TFGP1, SLCO1B3, CDX2 and KIF18A, the remaining model genes showed significant correlations with stem cell score, immune score and tumour microenvironment." (PMID 39656479, 2024). "Western Blot results of tumor tissues in mouse brain showed that when AAA237 was administered, the level of SKP2 was down-regulated, whereas the levels of SKP2 substrates P27 and P21 were up-regulated." (PMID 38341584, 2024). "Skp2 also mediates the ubiquitination and degradation of Amino-terminal enhancer of split (AES), which is a tumor and metastasis suppressor, and enhances tumor metastasis." (PMID 37089937, 2023). "In addition, S-phase kinase-associated protein 2 (Skp2) specifically degrades cyclin-dependent kinase inhibitor 1B (CDKN1B), and mindbomb homolog 1 (MIB1) enhances the ubiquitin-mediated degradation of suppression of tumorigenicity 7 (ST7); both Skp2 and MIB1 promote tumor proliferation." (PMID 38174069, 2023).
tumor (continued). "SKP2 shRNA silencing with shSKP2.1 and shSKP2.2 in FN-RMS cells strongly inhibited tumor-specific ability to form anchorage-independent colonies in soft agar 20 days after seeding compared to scrambled shRNA (shSCR)." (PMID 38102140, 2023). "Compound A (CdpA) inhibits Skp2-mediated p27 ubiquitination and Skp2 E3 ligase activity by excluding Skp2 from the SCF complex, thus inducing G1/S cell-cycle arrest and tumor cell killing." (PMID 37532777, 2023). "SET domain bifurcated histone lysine methyltransferase 1 (SETDB1) methylates Akt and functions as a scaffold to recruit JMJD2A, which then binds TRAF6 and Skp2-SCF to the Akt complex, thereby promoting tumor development in lung cancer." (PMID 35874839, 2022). "Several F‐box containing proteins have been characterized either as tumor suppressors (FBXW8, FBXL3, FBXW8, FBXL3, FBXO1, FBXO4, and FBXO18) or as oncogenes (FBXO5, FBXO9, and SKP2)." (PMID 33822486, 2021). "We found 5 potential target genes (SKP2, SMO, SDCBP, FERMT2 and PGAM1) that were consistently predicted by the three softwares and involved in tumor-related signaling pathway." (PMID 34221971, 2021). "In contrast to SKP2, FBXW7 is believed to function mainly as a tumor suppressor by targeting various oncogenic proteins for degradation." (PMID 33130827, 2021). "SKP2 induces tumorigenesis via Hippo signaling in HCC, and promotes tumor progression in breast cancer via PDCD4 ubiquitination." (PMID 34869393, 2021). "In the present study, we found that nobiletin inhibited tumor proliferation and progression in RCC by regulating the SKP2-p21/p27-CDK2 axis." (PMID 33628597, 2021). "Depletion of SKP2 and HIF-1α attenuated Mint3-mediated tumor sphere formation ability and chemoresistance in AsPC-1 cells." (PMID 32826949, 2020). "SKP2 can ubiquitinate and induce the degradation of the transcription factor FOXO1 which possesses a tumor suppressor function." (PMID 32226545, 2020). "Among the most significant genes we identified SKP2, IRF2 and MCM3, all related to tumor progression and metastases." (PMID 31533831, 2019). "Taken together, these results indicated that simvastatin repressed tumor growth by increasing p21 and p27 expression through AMPK activation and STAT3/Skp2 axis inhibition in vivo." (PMID 28230855, 2017). "Tumor tissues evaluated using IHC assay also showed that simvastatin treatment increased p21 and p27 expression, increased AMPK activation, decreased Skp2 expression and reduced STAT3 phosphorylation." (PMID 28230855, 2017). "The results of our tumor section evaluations by IHC showed that simvastatin treatment increased p21 and p27 expression and AMPK activation and decreased Skp2 expression and STAT3 phosphorylation." (PMID 28230855, 2017). "Finally, immunohistochemical staining of tumour tissues revealed that E269K-expressing tumour had increased proliferation index (increased Ki-67 and decreased p21), reduced apoptosis index (cleavage caspase-3) and increased SKP2 expression, whereas wild-type FBXW2 had just an opposite effect." (PMID 28090088, 2017). "In contrast with these data, FOXP3 was demonstrated to be a transcriptional repressor of two breast cancer oncogenes, SKP2 and HER2, acting as a potential tumor suppressor gene." (PMID 28903735, 2017). "We analyzed the levels of SIRT2 and Skp2 in age-controlled 28 NSCLC specimens, compared to paired adjacent non-tumor lung tissue (NT)." (PMID 26942878, 2016). "We found that the levels of SIRT2 significantly decreased, while the levels of Skp2 significantly increased in NSCLC specimens, compared to the paired non-tumor lung tissue." (PMID 26942878, 2016). "Many of the F box proteins function as oncoproteins (e.g., Skp2, NIPA and β-TRCP) or tumor suppressors (e.g., Fbxw7)." (PMID 26474281, 2015). "The analysis of 10 patients with tumors located in the oral cavity revealed increase in cell cycle regulatory SKP2 (p = 0.0214) and metabolic ACLY gene (p = 0.0403) in the tumor tissues compared to the healthy tissues." (PMID 25575813, 2015).
tumor (continued). "Some F-box proteins, such as SKP2, display oncogenic function, while other proteins, such as FBXW7,act as tumor suppressors." (PMID 25115392, 2014). "Literatures show that the oncogenic role of Skp2 always relies on the genetic status of PTEN, ARF, and Rb and other tumor suppression genes." (PMID 25015320, 2014). "Skp2 is the F-box protein responsible for substrate recognition in the Skp1-Cullin1-F-box (SCF) E3 ubiquitin ligase and specifically targeting the tumor suppressive proteins such as p27 for ubiquitination and proteasomal degradation." (PMID 24156782, 2013). "Cytoplasmic Skp2 expression correlated with AJCC stages (I vs II–IV, P<0.001), tumor thickness (≤2.00 vs >2.00 mm, P<0.001) and ulceration (P = 0.005)." (PMID 21386910, 2011). "While skp2 targets need to be phosphorylated prior to ubiquitination, the absolute amount of skp2 may also be important in determining target degradation; levels of skp2 protein itself are regulated in a cell cycle dependent manner while its levels are elevated in a number of human tumours." (PMID 18081928, 2007). "Its function results inactive in several human tumours, either by degradation via the SCF-type E3 ubiquitin ligase, Skp2 or by sequestration through Cyclin D3." (PMID 16740156, 2006). "SKP2 is sparsely overexpressed in hyperplasia, tumor adjacent tissues, PIN and adenocarcinoma with average percentage of positive SKP2 staining cells per core of 0.34%, 0.46%, 1.16%, and 2.43%, respectively, compared to that of normal prostate tissues (0.12%) (Ps < 0.05)." (PMID 41542047, 2026). "However, the administration of SKP2 inhibitors effectively reduced the proportion of the CD117+ subpopulation, thereby restoring the sensitivity of tumor cells to chemotherapy and enhancing treatment efficacy." (PMID 40271075, 2025). "Skp2 inhibitors like SKPin C1 and SMIP004 have shown tumor‐inhibitory effects." (PMID 39329019, 2024). "Reduction in SKP2:FOXA1 indicates that pharmaceutical inhibition of SKP2 is sufficient to target the SKP2–FOXA1 interplay and subsequently increase FOXA1 protein levels, while simultaneously suppressing tumor proliferation." (PMID 37491794, 2023). "The E3 ligase Skp2 ubiquitinates and activates AKT, which promotes the expression of downstream proteins, including glucose transporters and glycolytic enzymes, thus supporting glycolysis and tumor growth." (PMID 37176148, 2023). "A similar pattern of IHC staining for PCNA and FOXA1 protein levels was observed upon SKP2 inhibition, suggesting that SKP2 regulation of FOXA1 may, in turn, drive tumor proliferation and serve as in vivo validation for our in vitro findings." (PMID 37491794, 2023). "We further determined Skp2 levels in the NSCLC tissues and paired adjacent non-tumor tissues." (PMID 37532777, 2023). "Notably, the ablation of E3-ubiquitin ligases of Akt TRAF6, Skp2 and TRAF4 impairs tumor progression in vivo." (PMID 36769122, 2023). "SKP2 depletion unlocks a partly MYOD-dependent myogenic transcriptional program and strongly affects stemness and tumorigenic features and prevents in vivo tumor growth." (PMID 38102140, 2023). "Furthermore, the microRNA reversed the effect of circCRIM1 by promoting SKP2 expression and HCC proliferation, while SKP2 silencing attenuated the tumor-promoting capability of circCRIM1." (PMID 34869393, 2021). "Based on the results of our study, it is reasonable to view SKP2 expression as an indicator of tumor proliferation rather than as a single prognostic factor." (PMID 34414959, 2021). "Nobiletin downregulated mRNA expression of SKP2 by upregulating the transcription factor, FOXO3A, leading to accumulation of p21 and p27 and the reduction of CDK2, to inhibit cell proliferation and tumor formation." (PMID 33628597, 2021). "Notably, tumor sample analysis showed that RB1 protein abundance was slightly increased, while protein levels of CDK6, cyclin D3, cyclin E1, cyclin D1, SKP2, and CDK2 were significantly decreased in the combination treatment group." (PMID 34508104, 2021).